SMAD4 (SMAD family member 4)
Diseases named in the same sentence as SMAD4 in open-access papers (continued):
Sharing a sentence is not in itself a finding about the gene and the disease.
tumor (continued). "Nevertheless, Smad4 immunostain was markedly (1.4-fold and 1.9-fold, respectively) weaker in the tumorous tissues from early and advanced cancer stages compared with their corresponding normal specimens (p < 0.001)." (PMID 34867090, 2021). "Another promising candidate is SMAD4, a tumor suppressor that is the central node in TGF-β signaling." (PMID 33959500, 2021). "Meanwhile, Western blots indicated that the combination treatment decreased the expressions of p-Smad3 and N-cadherin, increased the expression of E-cadherin, and reduced nuclear accumulation of Smad4 in tumor tissues." (PMID 34324434, 2021). "Tumour suppressor SMAD4 is an essential modulator of the transforming growth factor (TGF)‐beta pathway controlling proliferation." (PMID 33624434, 2021). "SMAD4, a key downstream component in this system, was first isolated as a tumor-suppressor gene in human pancreatic ductal carcinomas." (PMID 34070531, 2021). "The tumour-associated macrophages (TAMs) provided cancer cells with trophic support, including TGF-β, to enable oncogenic KRAS bypass in a Smad4-dependent manner." (PMID 33671588, 2021). "In pancreatic cancer, for example, malic enzyme 2 (ME2) is frequently co-deleted along with the SMAD4 tumor suppressor, rendering tumor cells dependent on the only remaining mitochondrial malic enzyme isoform, ME3." (PMID 33540663, 2021). "Next generation sequencing analysis of the postoperative tumor tissue revealed that KRAS copy number was increased and detected SMAD4, RNF43, and PREX2 mutations." (PMID 34888240, 2021). "The subsequent restoration of SMAD4 re-established the sensitivity of these cells to the growth inhibitory effects of TGFβ, increased tumor latency, and decreased metastasis." (PMID 34680235, 2021). "In view of the pleiotropic functions of canonical TGF‐β signaling, Smad4 is extensively involved in tumor progression, playing drastically different roles in varied tumor models." (PMID 31721429, 2020). "Positive staining for SMAD4 confirmed the DNA vector activity and capability of providing sustained transgene expression following orthotropic injection and tumor development." (PMID 32420409, 2020). "Our group previously reported that Smad4 regulates murine NK cell homeostasis and maturation and anti-tumor Immunity." (PMID 33424832, 2020). "In PDAC, SMAD4 loss mediates PGK1 upregulation, which enhances glycolysis and contributes to aggressive tumor behavior." (PMID 32429474, 2020). "Conversely, one tumor pair shared missense mutations in three genes (EMSY, SMAD4, and POM121L12) and gene copy number amplification of three genes (SDHA, TERT, and EGFR)." (PMID 33139840, 2020). "Our findings showed that hsa_circ_0004872 acted as a tumor suppressor in GC by forming a negative regulatory loop consisting of hsa_circ_0004872/miR-224/Smad4/ADAR1." (PMID 33172486, 2020). "In contrast, mutations in Smad4 synergize with other oncogenic mutations (e.g., KrasG12D) to drive PDA progression and tumor growth." (PMID 33198201, 2020). "Next, we analyzed the impact of SMAD4 restoration in in vivo tumor growth by injecting CAPAN-1 luciferase or CAPAN-1 SMAD4-Luc cells orthotopically into the pancreas of NSG mice." (PMID 32420409, 2020). "SMAD4 inactivation can promote tumor progression and metastasis development in a tumor type-dependent manner." (PMID 32244895, 2020). "Tumor cells that express wildtype Smad4 undergo EMT following TGF-β stimulation, but ultimately apoptose." (PMID 33198201, 2020). "SMAD4 is recognized as an important tumor suppressor, but nuclear SMAD4 levels were significantly increased in HCC tumors." (PMID 32050622, 2020).
tumor (continued). "Patients with SMAD4 loss are commonly associated with distant disease progression, whereas patients with wild-type SMAD4 harbored a local tumor pattern of progression." (PMID 32429474, 2020). "All mice injected with parental or luciferase control cells developed invasive primary tumors, while those injected with SMAD4-restored tumor cells showed small and non-invasive accumulations of transplanted cells." (PMID 32420409, 2020). "We have previously identified a 4% and 29% mutation rate of Smad4 and Fat1 in HNSCC tissue samples, respectively, which are in agreement with the TCGA tumor database, the results of 4MOSCs analysis and the findings in present study." (PMID 33302499, 2020). "Accordingly, in a SMAD4/7 knock-out mouse model, SMAD4 was required for tumor formation, and a low level of SMAD7 expression promoted an invasive phenotype and metastatic spread associated with ZEB2/ZEB1 switching." (PMID 32759677, 2020). "In summary, we conclude that TGFBR3 is as a tumor suppressor via SMAD4-dependent and -independent manner in both tumor and stromal cells during oral carcinogenesis." (PMID 32471132, 2020). "SMAD4 is involved in numerous processes such as proliferation, differentiation and apoptosis, and many studies reported SMAD4 tumor suppressive activity." (PMID 32244895, 2020). "Smad4 is a tumor suppressor gene that was found to be frequently altered in CCA, inducing the activation of the proproliferative and antiapoptotic PI3K pathway." (PMID 32679791, 2020). "SMAD4 prevents the tumour-promoting activity of proinflammatory cytokines and induces cell cycle arrest and apoptosis in precancerous cells." (PMID 33008426, 2020). "Conversely, gain in KRAS, PIK3CA and SMAD4 alterations and scarce granzyme-B+ T-cells infiltration were observed when the tumor evolved towards a poly-metastatic spread." (PMID 33096795, 2020). "4-1BB aptamer has also been used in conjugation with an siRNA against Smad4 in the TGFβ signaling pathway, the signaling of which mediates immune suppression at the tumor microenvironment." (PMID 32316469, 2020). "The total weight of the pancreases was used as a measure of tumor growth, and mice injected with the SMAD4-restored cells had significantly smaller tumors than did mice injected with the unmodified parental line and GFP cell line." (PMID 32420409, 2020). "The 4-1BB aptamer-Smad4 siRNA conjugates rendered T cell resistant to TGFβ inhibition, and systemic administration of the conjugates to tumor-bearing mice boosted irradiation- and vaccine-induced antitumor immunity." (PMID 32316469, 2020). "SMAD4 is a common signaling during tumor progression, and it can inhibit cell proliferation and promote cell motility in most epithelial cells." (PMID 30745456, 2019). "Intact TGF-β/Smad4 signaling works as a tumor suppressor by blocking cell cycle progression, inducing apoptosis of epithelial cells, and maintaining genomic integrity and tissue hemostasis." (PMID 30832219, 2019). "SMAD4 is a signal transducer of the TGFß signaling pathway, which has a dual role as a tumor suppressor in early tumorigenesis, but a contrasting pro-metastatic role late in cancer development." (PMID 31383035, 2019).
tumor (continued). "Given that TGFβ signaling pathway can be either, tumor-suppressive or tumor-promoting, TGFβ/SMAD4-dependent pathway is considered tumor-suppressive by inducing cell cycle arrest and apoptosis." (PMID 31569425, 2019). "Previous studies have shown that SMAD4 also inhibits cell migration and that its downregulation affects tumour cell proliferation." (PMID 31684910, 2019). "Some of the genes involved include VEGFA (angiogenesis), WNT1 (proliferation), ERBB3 (proliferation), SMAD4 (tumor suppressor), NDRG2 (radioresistance) and EGFR (invasiveness) all leading to tumor aggressiveness." (PMID 30842790, 2019). "Although reduced TFEB expression was identified driving by secreted TGF-β in tumor-associated macrophages, we showed that treatment of TGF-β up-regulates TFEB in Smad4-positive PC cells." (PMID 31387632, 2019). "For the first time in the analysis of Smad4 immunohistochemical expression in UBC, our results suggested that there is a significant relationship between Smad4 and tumor grade and stage." (PMID 31238579, 2019). "SMAD4 inactivation is also common in pancreatic cancer development, and is found in 50% of patient cancers, disrupting the tumour suppressive signals of TGFβ, aiding proliferation." (PMID 31703358, 2019). "In the study presented here, we analyzed tumor samples by multiplex PCR-based next-generation sequencing (NGS) and found deleterious mutations of SMAD4 in 4.1% of the tumors." (PMID 31867281, 2019). "On the other hand, loss of SMAD4, a transcription factor in the TGF-β superfamily signaling, promotes tumor progression." (PMID 31756952, 2019). "Smad4 is involved in the signal transduction pathway of the transforming growth factor ß (TGF-ß) that acts as a tumor suppressor gene in several cancers." (PMID 31293968, 2019). "The expressions of TGF-β1, TGF-β2, SMAD4, E-cadherin, N-cadherin and Ki-67 in tumor xenografts were detected via immune- histochemical staining." (PMID 31631064, 2019). "Recently, TGF-β has been shown to be involved in the conversion of NK cells to ILC1-like cells, via a JNK-dependent, Smad4-independent pathway resulting in reduced cytotoxicity in murine tumor models." (PMID 31333651, 2019). "Another tumour suppressor gene that is commonly deregulated in PC is the pancreatic carcinoma 4 gene (DPC4, also known as SMAD4), which is upregulated in 55% of PC." (PMID 31752758, 2019). "SMAD4, a central mediator of transforming growth factor beta (TGFβ) signaling pathway, is considered a tumor suppressor gene." (PMID 31569425, 2019). "Eighty–one tumor (20%) showed uniform expression of Smad2 and Smad4, while 172 (42.57%) tumors were scored as simultaneously negative/low for the expression of both markers." (PMID 31238579, 2019). "It is still necessary to further explore the mechanism whereby SMAD4 Y353C acts as a tumour suppressor gene and, thus, provide a firmer theoretical basis for PDAC treatment." (PMID 31684910, 2019). "This study supports the key role of SMAD4 as a tumour suppressor gene in PDAC and shows that SMAD4 Y353C is associated with poor progression of PDAC." (PMID 31684910, 2019).
tumor (continued). "These experimental and observational results suggest that SMAD4-deletion in CRC causes both cancer cell phenotype and tumor microenvironment to switch to the more aggressive cancer phenotype." (PMID 31756952, 2019). "TRIM47 exerts an inhibitory effect on SMAD4 by ubiquitylating and degrading SMAD4, thereby promoting tumor growth and progression." (PMID 30979374, 2019). "Smad proteins, including R-Smads and Smad4, mediate both the tumor-inhibitory and promoting effects of TGF-β." (PMID 31614569, 2019). "Most of the PDAC tumour tissues were stained with SMAD4 in the cytoplasm, and some of them exhibited expression in the interstitial fibrous tissue of the tumour." (PMID 31684910, 2019). "This was a surprising finding because SMAD4 has been identified as a tumour-suppressor gene, but TGFβ1 signalling is the main effector in pulmonary fibrosis." (PMID 30704051, 2019). "As with the genes involved in the JAK/STAT3 pathway, 10 mg/kg ajoene extract significantly suppressed the expression of Smad2, Smad3, and Smad4 compared with the tumor control group (Smad2, p = 0.012; Smad3, p = 0.049; Smad4, p < 0.001)." (PMID 31717643, 2019). "We also mapped our data with top 20 mutated genes in CRC from COSMIC data sets and found FAT1 and FAT4 to be mutated in tumour, whereas distal margin showed the presence of FAT1, KRAS and SMAD4 mutations." (PMID 30950180, 2019). "Smad4 inactivation results in ligand accumulation that signal in tumor cells (in a Smad-independent manner) as well as in stromal cells." (PMID 30832219, 2019). "As a central component of TGF-β signaling, SMAD4 status is likely to exert a prominent effect on host-tumor cross-talk relevant to cancer progression." (PMID 31480737, 2019). "SMAD4 is a classical tumor suppressor gene, and acts to regulate the transforming growth factor-β (TGF-β) signaling pathway." (PMID 30477242, 2018). "Correspondingly, the expression of SMAD4 was distinctly upregulated in the tumor with miR-301a inhibition." (PMID 30185897, 2018). "As we all know, SMAD4 had been recognized as a tumor suppressor gene in a good deal of cancers, and recent study had presented that SMAD4 suppressed the progression of RCC by targeting various downstream genes." (PMID 30419914, 2018). "LOH of DCC, BCL2, and SMAD4 were validated using microsatellite marker quantification between tumor and matched normal samples for each specific locus." (PMID 30219970, 2018). "As we expect, the effect of miR-301a inhibition on restraining tumor growth was reversed by the presence of Smad4 shRNA in transformed BEAS-2B cells." (PMID 30185897, 2018). "Several pieces of evidence have proved that Smad4 is inactivated in GC and acts as a tumor suppressor in GC." (PMID 29103082, 2018). "The clinicopathological data showed that Smad4 expression was negatively correlated with tumor size." (PMID 29103082, 2018). "In the case of the PTEN, FBXW7 and SMAD4 genes, as well as several other tumor suppressors, a frequent mechanism of inactivation is through point mutations that reoccur at the defined residues and act dominantly on the molecular level." (PMID 29572294, 2018). "The tumor suppressor gene SMAD4 mediates the TGFb signaling pathway suppressing epithelial cell growth." (PMID 29467924, 2018). "SMAD4 expression has also been shown to be important for anti-tumor activity in circulating immune cells such as T cells and NK cells." (PMID 30477242, 2018).
tumor (continued). "The common loss of SMAD4 in PDAC results in the upregulation of TGF-β signalling, which aids in tumour progression via the activation of MAPK/ERK, PI3K/AKT, p38 MAPK and Rho-GTPase pathway signalling." (PMID 29382042, 2018). "It has been reported that Smad4 was inactivated in different types of carcinomas and acted as a tumor suppressor in GC." (PMID 29103082, 2018). "A positive effect of TGFβ on NK cell function was suggested in a recent study demonstrating that TGFβ signaling increases NK cell anti-tumor activity, as SMAD4−/− murine NK cells had decreased cytotoxicity." (PMID 30400618, 2018). "In this study, we found the well-known driver genes MAPK1, PIK3CA and SMAD4 to be private to either the primary tumour or the metastasis." (PMID 30029640, 2018). "KRAS G12D is a well-studied oncogenic driver, whereas the co-occurrence of R361C and R361H in SMAD4 indicated biallelic inactivation of this tumor suppressor [15−18]." (PMID 30220971, 2018). "Subsequently, cell gain and loss function assay showed that miR-205 suppressed cell viability by targeting SMAD4, suggesting that miR-205 serves as a tumor suppressor mainly through regulating the function of SMAD4." (PMID 29290978, 2017). "Smad4 protein levels in wild-type prostate tissue are relatively low, but when the tumor suppressor phosphatase and tensin homolog (Pten) is lost, Smad4 levels increase, suggesting that Smad4 acts to constrain tumor progression." (PMID 29113300, 2017). "Further, a borderline significant shorter survival was found for those with low SMAD4 protein levels in the nuclei with Smad4 LOH positive in stage III CRC patients, indicating that Smad4 is a tumor suppressor gene for these 18q21 deletions at the Smad4 locus." (PMID 28423626, 2017). "To this end, we measured the protein levels of cyclin D1, phospho-Smad2/3, and Smad4 in 40 of HCC tumor tissues." (PMID 28415588, 2017). "Our results demonstrate that low nuclear SMAD4 tumor protein in stage III and high cytoplasmic protein levels in stage II tumors are markers of poor prognosis for CRC patients." (PMID 28423626, 2017). "In summary, Smad4 has been regarded primarily as a tumor suppressor downstream of TGF-β signaling, with relatively little known about its role in the nervous system." (PMID 29183317, 2017). "Among the predicted miR-27a targets, the SMAD4 gene was chosen for further analysis as all three prediction methods listed SMAD4 as a top candidate and miR-27a has an established role in the inhibition of tumor metastasis." (PMID 29065177, 2017). "In normal pancreatic cells, TGF-β/Smad4 signaling induces a tumor suppressive effect mediated through Smad4-regulated genes." (PMID 28067794, 2017). "Some cancer cells escape the tumour suppressor effects of TGF-beta by down-regulation/mutation of the type 1 and 2 receptors, Smad2 and Smad4." (PMID 29267390, 2017). "SMAD4-dependent TGF-β signaling is common during tumor development and progression; can inhibit cell proliferation, promote cell motility and the EMT process in most epithelial cells; and affects sensitivity to clinical therapy." (PMID 28199217, 2017). "SMAD4 was first identified as a tumor suppressor in pancreatic cancer 6, and subsequently was characterized as a key molecule in transforming growth factor (TGF)‐β signaling." (PMID 28256094, 2017). "Among this protein family, SMAD4 (localized to band 18q21) has a central role as a common downstream regulator and tumor suppressor gene." (PMID 28267766, 2017). "As an important mediator of the TGF-β signaling pathway, SMAD4 plays an important role in suppressing tumor progression and promoting apoptosis of tumor cells." (PMID 28938919, 2017).